PRAMEF4 (PRAME family member 4)
Synonyms: RP5-845O24.6
Tractability: No criterion of Open Targets' tractability assessment is met for any kind of drug.
Gene: Protein-coding gene on chromosome 1 (12,879,212 to 12,886,201, reverse strand). Ensembl gene ENSG00000243073.
Gene Ontology:
Molecular function: ubiquitin-like ligase-substrate adaptor activity
Biological process: proteasome-mediated ubiquitin-dependent protein catabolic process; negative regulation of apoptotic process; negative regulation of cell differentiation; negative regulation of DNA-templated transcription; positive regulation of cell population proliferation
Cellular component: Cul2-RING ubiquitin ligase complex; cytoplasm
Genetic constraint (gnomAD): Loss-of-function variants: 18 observed, 28.05 expected, observed/expected ratio (o/e) 0.64, 90% interval 0.44 to 0.95. The upper end of that interval is the gene's LOEUF score, 0.95, which puts it in group 4 of 6, group 1 being the genes least tolerant of losing a copy. Missense variants: 481 observed, 462.07 expected, observed/expected ratio (o/e) 1.04, 90% interval 0.96 to 1.12. Synonymous variants: 156 observed, 164.69 expected, observed/expected ratio (o/e) 0.95, 90% interval 0.83 to 1.08.
Homologues: Orthologues: mouse Pramel13 (45% identical), rat Pramef12 (44% identical), rat Pramef8 (43% identical), mouse Pramel15 (43% identical), mouse Pramel12 (42% identical), mouse Pramel16 (42% identical), rat Pramel36l1 (42% identical), rat LOC120103107 (42% identical), mouse Pramel31 (42% identical), rat LOC134481896 (42% identical), rat Pramef20 (42% identical), rat Pramef20l1 (42% identical), and 78 more. Paralogues in human: PRAMEF15 (98% identical), PRAMEF25 (96% identical), PRAMEF26 (96% identical), PRAMEF5 (96% identical), PRAMEF11 (96% identical), PRAMEF6 (96% identical), PRAMEF9 (96% identical), PRAMEF27 (95% identical), PRAMEF20 (81% identical), PRAMEF12 (61% identical), PRAMEF8 (61% identical), PRAMEF7 (61% identical), and 12 more.
Diseases named in the same sentence as PRAMEF4 in open-access papers:
PRAMEF4 is named in the same sentence as 2 diseases in open-access papers, as found by Europe PMC text mining. Sharing a sentence is not in itself a finding about the gene and the disease.
PRAMEF4 shares sentences with these, for which no sentence is quoted: melanoma (1 paper); Obesity (1).